KCNRG (potassium channel regulator)
Description:
Inhibits potassium fluxes in cells. May regulate Kv1 family channel proteins by retaining a fraction of channels in endomembranes.
Synonyms: DLTET
Tractability: No criterion of Open Targets' tractability assessment is met for any kind of drug.
Gene: Protein-coding gene on chromosome 13 (50,015,254 to 50,020,922, forward strand). Ensembl gene ENSG00000198553.
Subcellular location: Endoplasmic reticulum
Subcellular location (Human Protein Atlas): Golgi apparatus; Vesicles; Basal body
Gene Ontology:
Molecular function: identical protein binding; protein binding
Biological process: negative regulation of delayed rectifier potassium channel activity; protein homooligomerization
Cellular component: endoplasmic reticulum
Genetic constraint (gnomAD): Loss-of-function variants: 18 observed, 17.82 expected, observed/expected ratio (o/e) 1.01, 90% interval 0.7 to 1.5. The upper end of that interval is the gene's LOEUF score, 1.5, which puts it in group 6 of 6, group 1 being the genes least tolerant of losing a copy. Missense variants: 306 observed, 335.09 expected, observed/expected ratio (o/e) 0.91, 90% interval 0.83 to 1. Synonymous variants: 97 observed, 122.61 expected, observed/expected ratio (o/e) 0.79, 90% interval 0.67 to 0.94.
Homologues: Orthologues: chimpanzee KCNRG (99% identical), macaque KCNRG (94% identical), pig KCNRG (86% identical), rabbit KCNRG (85% identical), mouse Kcnrg (72% identical), tropical clawed frog kcnrg (57% identical), Drosophila melanogaster twz (18% identical), Caenorhabditis elegans F32B4.5 (13% identical). Paralogues in human: KCTD12 (24% identical), KCTD11 (24% identical), KCTD1 (23% identical), KCTD15 (23% identical), KCTD16 (22% identical), KCTD8 (22% identical), KCTD21 (21% identical), KCTD6 (20% identical), KCTD18 (19% identical), KCTD7 (18% identical), KCTD14 (18% identical), KCTD19 (17% identical), and 1 more.
Diseases named in the same sentence as KCNRG in open-access papers:
KCNRG is named in the same sentence as 19 diseases in open-access papers, as found by Europe PMC text mining. Sharing a sentence is not in itself a finding about the gene and the disease. The quoted sentences say what the papers report.
pneumonitis (5 papers, 2017 to 2024). An inflammatory process affecting the lung parenchyma. "In addition, some thymoma patients carry autoantibodies against the lung-targeted bactericidal/permeability-increasing fold-containing B1 (BPIFB1), the potassium channel regulator (KCNRG), or both, which are also seen in APECED-associated pneumonitis." (PMID 38954150, 2024). "Titers of BPIFB1 and KCNRG autoantibodies did not decline despite clinical and radiographic remission of pneumonitis, further suggesting that the pathogenic role of B-cells might be conferred via priming of T-cells in the lung tissue, rather than through autoantibody production." (PMID 33584685, 2020). "While the levels of KCNRG autoantibodies seen in adults with COVID-19 occurred at a higher frequency than that seen in adults with ARDS (23%) or sepsis (25%), they were lower than those reported in other diseases such as APECED complicated by pneumonitis (29%)." (PMID 35360001, 2022). "Autoantibodies against a putative potassium channel regulator (KCNRG) were found in the sera of approximately 28% of APECED patients with pneumonitits and 0% of APECED patients without pneumonitis." (PMID 31548517, 2017). "In addition to KCNRG, antibodies to bactericidal/permeability-increasing fold-containing B1 (BPIFB1) of the bronchial epithelium have been identified in 85.7% and 14.3% of APECED patients with and without pneumonitis, respectively." (PMID 31548517, 2017).
pulmonary disease (4 papers, 2012 to 2024). "Beyond performing a chest CT, measurement of autoantibodies against BPIFB1 and KCNRG is a valuable diagnostic tool and should be considered as a screening modality in patients with thymoma and radiographic evidence of lung disease and/or chronic respiratory symptoms." (PMID 38954150, 2024). "Previously, anti-KCNRG autoantibodies were identified as a biomarker of pulmonary disease in autoimmune polyendocrine syndrome type I patients, a condition with a high co-occurrence of T1D." (PMID 23028856, 2012). "Autoantibodies directed against the potassium channel regulatory protein (KCNRG) and BPIFB1, found in epithelial cells of terminal bronchioles, have been suggested as a marker for pulmonary disease in APECED patients." (PMID 27597936, 2016). "Autoantibodies directed against the potassium channel regulatory protein (KCNRG), found in epithelial cells of terminal bronchioles, have been suggested as a marker for pulmonary disease in APECED patients." (PMID 23133448, 2012).
autoimmune conditions (2 papers, 2012 to 2024). "Based on the literature, autoantibodies were also tested against six potential organ–specific antigens implicated in T1D and/or other autoimmune conditions including ATP4B, TGM2, TPO, KCNRG, AQP-4, and GFAP." (PMID 23028856, 2012). "Of note, most of these patients were negative for other autoantibodies associated with autoimmunity and/or lung autoimmunity in other conditions (KCNRG, BPIFB1, TRIM38, CENP-A, interferon-ω, ABLIM, and CDHR) suggesting some specificity for ILD in the context of SjD." (PMID 39524452, 2024).
Sepsis (2 papers, 2010 to 2022). Sepsis is defined as life-threatening organ dysfunction caused by a dysregulated host response to infection. "The most frequent autoantigen target in ARDS and sepsis was KCNRG, a protein highly expressed in the lung." (PMID 20946647, 2010). "Mann Whitney U test analysis revealed significantly higher detectable anti-KCNRG autoantibody titers in both the ARDS (P < 0.006) and sepsis patient groups (P < 0.03) compared to the controls." (PMID 20946647, 2010). "Although the anti-KCNRG autoantibody titers were modestly elevated compared to the anti-cytokine autoantibodies, 23% (8/35) of the ARDS and 25% (3/12) of the sepsis patients had statistically significant autoantibody titers that were higher than the control cut-off." (PMID 20946647, 2010).
autoimmune polyendocrinopathy-candidiasis-ectodermal dystrophy (1 paper, 2024). "Autoantibody testing against two other autoantigens, KCNRG and BPIFB1, found in autoimmune polyendocrinopathy-candidiasis-ectodermal dystrophy (APECED) patients with autoimmune pneumonia, revealed no seropositivity in any of the SjD or IIM subjects (data not shown)." (PMID 39524452, 2024).
bronchiectasis (1 paper, 2021). Segmental, irreversible dilation of the bronchial tree resulting in the accumulation of secretions which leads to obstruction. "A bronchoscopy should be performed in patients with radiographic evidence of bronchiectasis and/or ground glass or nodular opacities and/or in patients with abnormal pulmonary function testing, even when BPIFB1 and/or KCNRG autoantibodies are negative." (PMID 34790633, 2021).
COVID-19 (1 paper, 2022). A disease caused by infection with severe acute respiratory syndrome coronavirus 2. "Here we show that 30% of adults with COVID-19 had autoantibodies against the lung antigen KCNRG, and 34% had antibodies to the SLE-associated Smith-D3 protein." (PMID 35360001, 2022). "Samples from children with COVID-19 or MIS-C were also examined to determine if there was immunoreactivity against additional autoantigens including KCNRG, PLA2R, GAD65, and gastric intrinsic factor (GIF)." (PMID 35360001, 2022). "Detection of autoantibodies to KCNRG is consistent with the lung injury and dysfunction that occur in many hospitalized COVID-19 patients." (PMID 35360001, 2022). "Analysis of adult patients with COVID-19 showed a moderate frequency of autoantibody positivity against several autoantigens including the lung protein KCNRG (30%) and the SLE antigen Sm-D3 (34%)." (PMID 35360001, 2022). "Low levels of autoantibodies to KCNRG, a lung antigen, were found in 30% (24/80) of adult COVID-19 patients and were significantly enriched in the patients with severe or moderate disease and generally absent from patients with critical or mild disease (Fisher Exact test; P<0.003)." (PMID 35360001, 2022). "Taken together, these results suggest that adults with COVID-19 had a diverse repertoire of serum autoantibodies to known autoantigens and at least two of them, the lung KCNRG and stomach gastric ATPase, might reflect infection-related damage to these tissues in selected patients." (PMID 35360001, 2022). "In contrast to adults, most children with COVID-19 demonstrated little or no autoantibodies against KCNRG, Sm-D3, and the other autoantigens we tested." (PMID 35360001, 2022). "Our analysis showed a moderate prevalence of autoantibodies targeting the lung antigen KCNRG in adults, but not in children with COVID-19." (PMID 35360001, 2022). "Moreover, both KCNRG and Sm-D3 autoantibodies were enriched in COVID-19 adult patients with severe and moderate disease, but not in critically ill COVID-19 patients." (PMID 35360001, 2022).
hepatocellular carcinoma (1 paper, 2021). A malignant tumor that arises from hepatocytes. "Sequencing analysis of 77 Hepatocellular carcinomas (HCCs) showed that KCNRG can be mutated in HCC tumors." (PMID 34001146, 2021). "Similarly to leukemia cells, KCNRG overexpression suppresses the growth activity of Hep3B hepatoma cells while its inactivation, through mutations or allelic losses, contributes to the development or progression of HCC." (PMID 34001146, 2021).
leukemia (1 paper, 2021). A malignant (clonal) hematologic disorder, involving hematopoietic stem cells and characterized by the presence of primitive or atypical myeloid or lymphoid cells in the bone marrow and the blood. "KCNRG overexpression in leukemia cell lines exerts growth suppression, promotes apoptosis, leads to changes in size and shape, and causes the decrease of cell migration capacity." (PMID 34001146, 2021).
Parkinson disease (1 paper, 2022). A progressive degenerative disorder of the central nervous system characterized by loss of dopamine producing neurons in the substantia nigra and the presence of Lewy bodies in the substantia nigra and locus coeruleus. "On the other hand, the top gene sets enriched in the ACC of both sexes were related with mitochondrial function, potassium channel regulator activity, extracellular matrix, Parkinson’s disease, oxidative phosphorylation as well as complement and coagulation cascades." (PMID 35663269, 2022).
Tumor (3 papers, 2016 to 2024). "Tumor tissues and cell lines can also have reduced expression of the potassium channel regulator KCNRG, which reduces K+ currents across the plasma membrane and reduces cell proliferation." (PMID 38527087, 2024).
KCNRG also shares sentences with these, for which no sentence is quoted: chronic lymphoid leukemia (2 papers); acute myeloid leukemia (1); autoimmune polyendocrine syndrome (1); B-cell chronic lymphocytic leukemia (1); bacterial meningitis (1); cancer (1); infection (1); thymoma (1).